SIN3A (SIN3 transcription regulator family member A)
Diseases named in the same sentence as SIN3A in open-access papers (continued):
Sharing a sentence is not in itself a finding about the gene and the disease.
breast carcinoma (continued). "This study identifies Sin3A as an essential regulator of growth and survival of ERα-positive breast cancer cells, which may have important translational implications for breast cancer patients." (PMID 20920219, 2010). "Interestingly, we also find that estrogen causes an increase in Sin3A protein levels in ERα-positive cells, suggesting the involvement of Sin3A in a feedback circuit regulating estrogen-dependent growth of breast cancer cells." (PMID 20920219, 2010). "Additionally, SIN3A knockdown increased the metastatic potential of breast cancer cells." (PMID 35681732, 2022). "Additionally, in breast cancer metastasis Sin3A and B have opposite effects." (PMID 33652591, 2021). "Besides, interaction of FOXN3 with NEAT1/SIN3A showed to repress GATA3 in breast cancer metastasis." (PMID 30894512, 2019). "In the breast cancer tissue containing the SIN3A mutant, its distribution was mostly correlated with the tumor regions showing nuclear enlargement as observed in transcriptional activation, indicating that SIN3A mutant plays an important role in the progression of breast cancers." (PMID 30375428, 2018). "Breast cancer metastasis suppressor 1 like (BRMS1L), a core component of the Sin3A–histone deacetylase (HDAC) co-repressor complex, has been reported to suppress breast cancer metastasis through epigenetically regulating the Wnt signal pathway." (PMID 41282485, 2025). "In various breast cancer mouse models, we found that SAP30 promoted tumor growth and metastasis through its interaction with SIN3A/3B." (PMID 37655663, 2023). "The SIN3A-HDAC complex is recruited to the promoter of GATA3 by FOXN3 to repress GATA3 expression, thus repressing breast cancer metastasis." (PMID 37291119, 2023). "Our study has made groundbreaking progress in identifying key transcription factors, such as SP1, E2F1, and SIN3A, as well as kinases, including MAPK14, CSNK2A1, and CDC2, whose role in breast cancer progression is paramount." (PMID 38084295, 2023). "Taken together, these results indicate that MLL1 interacts with SAP30/SIN3A and acts as a downstream executor to control the transcription of SAP30/SIN3-coactivated genes in breast cancer cells by increasing H3K4me3 levels." (PMID 37655663, 2023). "This binding model suggests that SAP30 acts as a molecular hub connecting with SIN3A and MLL1 to coordinate gene transcription in breast cancer cells." (PMID 37655663, 2023). "The ZNF704/SIN3A complex represses a panel of genes, including PER2, resulting in the proliferation and invasion of breast cancer." (PMID 37291119, 2023). "Using human breast cancer cells transfected with MAD1 SID or treated with the MAD SID peptide, we observed a dissociation of MAD1, RARα and RARβ from Sin3A in a coimmunoprecipitation assay." (PMID 35406744, 2022). "The cytoplasmic localization attenuates the functions of SIN3A, leading to an increase in ESR1 expression that accelerates the cell proliferation involved in the progression of breast cancers." (PMID 30375428, 2018). "We compared SIN3A and SIN3B gene expression with relapse-free survival of patients with breast cancer." (PMID 27780928, 2016). "Future work will be necessary to fully understand specific targets regulated by SIN3A and SIN3B and in what context or molecular subtype of breast cancer." (PMID 27780928, 2016). "This is consistent with recent studies demonstrating inhibition of breast cancer invasion using SIN3 interacting domain decoy peptides and small molecule inhibitors of SIN3 that inhibit both SIN3A and SIN3B." (PMID 27780928, 2016). "We find that Sin3A regulates the expression of several genes important in breast cancer and estrogen signaling, and these effects are mediated through both HDAC1/2-dependent and -independent mechanisms of Sin3A." (PMID 20920219, 2010). "Our lab previously showed that Sin3A regulated the estrogen-induced repression of the ERα gene, ESR1, in the MCF7 breast cancer cell line." (PMID 20920219, 2010).
breast carcinoma (continued). "Our previous report shows that Sin3A controls expression of the ERα gene itself, ESR1, and Sin3A can interact with ERα in ERα-positive breast cancer cells." (PMID 20920219, 2010). "We previously showed that the Sin3A transcriptional repressor protein is a regulator of estrogen-induced repression of the ERα gene, ESR1, in breast cancer cells." (PMID 20920219, 2010). "Genes of known importance in breast cancer and estrogen signaling, including ERBB2, PGR, MYC, CLU, and NCOA2, were among those identified as Sin3A-responsive." (PMID 20920219, 2010). "The specific finding of SIN3a as a pro-survival factor highlights the importance of the estrogen-mediated survival of breast cancer cells, where SIN3a knockdown increases apoptosis without affecting the cell cycle." (PMID 38275371, 2023). "At the same time, NEAT1, which is induced by estrogen in breast cancer, can form FOXN3-NEAT1-SIN3A inhibitory factor, through the interaction with FOXN3 and SIN3A protein complex, and promote epithelial-mesenchymal transformation (EMT) and metastasis, diffusion and invasion of breast cancer cells." (PMID 34804040, 2021). "Our study proclaimed that the altered phosphorylation of two potential transcription factors of GOLT1B, JUN and SIN3A, might be responsible for the increased GOLT1B expression in breast cancer." (PMID 35127514, 2021). "Our data shows that high expression of either SIN3A or SIN3B correlates with longer relapse-free survival of patients with breast cancer when samples were not stratified." (PMID 27780928, 2016). "Additionally, we analyzed microarray data sets to identify correlations of SIN3A and SIN3B expression with survival in patients with breast cancer." (PMID 27780928, 2016). "Although we have not validated these gene sets by analyzing the expression of individual genes, the data support our hypothesis that SIN3A and SIN3B have differential functions in breast cancer progression." (PMID 27780928, 2016). "Together, these results demonstrate differential gene regulation by SIN3A and SIN3B that may help to explain reasons for the functional differences in breast cancer." (PMID 27780928, 2016). "The differential roles of SIN3A and SIN3B in breast cancer progression is not completely unexpected considering that knockout mice for either Sin3A or Sin3B is embryonic lethal at different stages of development." (PMID 27780928, 2016). "Sin3A regulates the transcription of genes involved in breast cancer and apoptosis and acts through multiple mechanisms not limited to histone deacetylase function." (PMID 20920219, 2010). "Previous studies had suggested a role for Sin3A in growth of normal and neoplastic cells, but the function of Sin3A in breast cancer had not been fully explored." (PMID 20920219, 2010). "This suggests that differences in Sin3A expression would not be found in microarray studies, possibly explaining why the role of Sin3A in breast cancer has not been appreciated until now." (PMID 20920219, 2010). "In both cases, broadlyaccepted breast cancer drivers such as BRCA1 and ESR1 are central nodes in the network.The network analysis has revealed severalinfluential DCDs that are not curated CGC genes yet, for example E2F2 and THRA fromsingle-cell, and SIN3A from bulk data." (PMID 36124841, 2022). "Previously, we have established that blocking the PAH2-mediated Sin3A interaction with SID-containing proteins using SID peptides or small molecule inhibitors (SMI) increased RARβ expression and induced retinoic acid metabolism in breast cancer cells, both in in vitro and in vivo models." (PMID 35406744, 2022). "We hypothesized that SIN3A and SIN3B play differential roles during breast cancer progression." (PMID 27780928, 2016).
breast carcinoma (continued). "Together, these data show that Sin3A differentially regulates the expression of apoptotic genes in ERα-positive MCF7 cells and ERα-negative MDA-MB-231 cells, which may selectively influence the growth and survival of the ERα-positive subtype of breast cancer." (PMID 20920219, 2010). "After a multi-omics analysis, we uncovered that the higher expression of GOLT1B in breast cancer tissues versus normal tissues might be due to the amplification of GOLT1B and altered phosphorylation of its potential transcriptional factors, including JUN and SIN3A." (PMID 35127514, 2021). "Importantly, decreased Sin3A expression led to an increase in apoptosis and increased expression of several apoptotic genes, which translated into attenuation of cell growth of ERα-positive and not ERα-negative breast cancer cells." (PMID 20920219, 2010). "TRAIL, TRAILR1, TRAF4, CASP10, and APAF1 increase upon Sin3A knockdown in MCF7, but not MDA-MB-231, breast cancer cells." (PMID 20920219, 2010). "However, specific roles for SIN3A and SIN3B in breast cancer progression have not been characterized." (PMID 27780928, 2016).
lung carcinoma (9 papers, 2022 to 2025). "It was demonstrated that the lower expression of SIN3A was associated with more aggressive lung cancer progression." (PMID 35681732, 2022). "We found that LINC00265 binds to and stabilizes SIN3A protein in lung cancer cells, thus identifying a novel partner for this LncRNA." (PMID 38948024, 2024). "Silencing of SIN3A also reduced proliferation of lung cancer cells, which was correlated with the induction of autophagy." (PMID 38948024, 2024). "miR-210 regulates the target gene SIN3A in human lung cancer to participate in proliferation and apoptosis in non-small cell lung cancer (NSCLC)." (PMID 36361761, 2022). "Therefore, LINC01279 promoted the occurrence and development of lung cancer by regulating FAK and SIN3A to inhibit autophagy in lung cancer cells." (PMID 40438586, 2025). "Besides, due to the decrement of expression level, the attenuated function of gene SIN3A (ranked 93th in patient TCGA-E9-A1N6) may lead to the epigenetic deregulation of the growth-associated genes, which results in the oncogenesis of lung cancer cells." (PMID 38254011, 2024). "Therefore, this expression profile of autophagy-related proteins is similar as observed in LINC00265-knockdown cells, suggesting that LINC00265 and SIN3A may function together to regulate lung cancer development." (PMID 38948024, 2024). "In the current study, we reveal that nuclear C3b acts as a cofactor of the chromatin remodeling SIN3A complex to repress the expression of GADD45A, thus conferring acquired resistance of lung cancer to PTX treatment." (PMID 37291119, 2023). "To determine whether SIN3A is functional in conjunction with BRD3, we conducted an experiment on siRNA‐mediated knockdown of the SIN3A gene in H1299 and A549 lung cancer cell lines." (PMID 34605158, 2022).
Intellectual disability (6 papers, 2018 to 2025). "Recent discoveries have linked SIN3A mutations to several cases of autism spectrum disorder and mild intellectual disability." (PMID 39843641, 2025). "Patients with SIN3A variants adversely affecting protein function have mild intellectual disability, growth and feeding difficulties." (PMID 33437032, 2021). "Heterozygous loss-of-function variants in SIN3A were recently described to result in a novel neurodevelopmental syndrome comprising intellectual disability and varying degrees of developmental delay." (PMID 33437032, 2021). "Indeed, functional studies have revealed that SIN3A is a key regulator of cortical expansion and maturation, and its haploinsufficiency has been associated with intellectual disability and autism spectrum disorder." (PMID 40018685, 2025).
glioblastoma (5 papers, 2021 to 2026). The most malignant astrocytic tumor (WHO grade IV). "Another recent study found T cells in the TME and peripheral blood that reacted to the glioblastoma neoantigen SIN3A* as well as to peptides produced by the microbiota." (PMID 40264971, 2025). "While our data show that the interaction of THOC1 and SIN3A regulates R-loops globally, the impact on glioblastoma may be disproportionately driven by its impact on telomeres." (PMID 41496272, 2026). "Furthermore, cytotoxic activity against autologous glioblastoma cells was comparable after stimulation with SIN3A* or HGM3 peptides." (PMID 37198490, 2023). "As an example, TCC8F7 strongly responds to the SIN3A*-derived and several other glioblastoma-derived peptides, but not any of the bacterial antigens." (PMID 37198490, 2023).
non-small cell lung carcinoma (5 papers, 2016 to 2023). A group of at least three distinct histological types of lung cancer, including non-small cell squamous cell carcinoma, adenocarcinoma, and large cell carcinoma. "A previous study showed that SIN3a is reduced in 19 of 31 cases (61%) of non-small-cell lung cancers, and its absence may alter the expression of growth-related genes in an epigenetic-dependent manner through histone acetylation, leading to tumorigenesis in lung cancer cells." (PMID 38275371, 2023).
pulmonary fibrosis (5 papers, 2021 to 2024). Chronic progressive interstitial lung disorder characterized by the replacement of the lung tissue by connective tissue, leading to progressive dyspnea, respiratory failure, or right heart failure. "In contrast, progressive pulmonary fibrosis was observed in Sin3a loss-of-function mice with AT2 cell senescence in addition to AT2 cell loss." (PMID 39699958, 2024). "A previous study suggested that loss of Sin3A drives alveolar type 2 cell dysfunction and progressive lung fibrosis in mice." (PMID 37312162, 2023).
Witteveen-Kolk syndrome (5 papers, 2021 to 2026). "Recently, hypogonadotropic hypogonadism has been suggested to overlap with Witteveen-Kolk syndrome (WITKOS, OMIM #613406) associated with 15q24 microdeletions encompassing SIN3A." (PMID 38528912, 2024). "A Whole Exome Sequence showed mutations in KDM3B and SIN3A genes, respectively responsible for Diets-Jongmans syndrome (DIJOS) and Witteveen-Kolk syndrome (WITKOS)." (PMID 38314229, 2023). "Here, we relate αα-hub stability to function by structural and thermodynamic studies of the Sin3A-paired amphipathic helix 1 (PAH1) wt hub domain and two predicted loss-of-function variants (A126V and K155E) found in patients with the neurodevelopmental Witteveen-Kolk syndrome." (PMID 41759735, 2026). "In patient 37, a (heterozygous in-frame-deletion) VUS in the SIN3A gene was found, which could be linked to the patient’s ID and behavioral problems; however, the patient had tall stature and no dysmorphisms associated with Witteveen-Kolk syndrome." (PMID 37889289, 2024).
developmental delay (4 papers, 2020 to 2024). "Patients with disease causing variants in SIN3A usually have mild global developmental delay/ID, with some even having tested IQs in the normal range with variable penetrance." (PMID 33437032, 2021). "Enrichment analysis for upstream transcription factors of these 272 co-expressed proteins highlighted components related to neurodevelopment and Hippo signaling, including SIN3A, and to human diseases such as developmental delay and mental retardation." (PMID 39174523, 2024). "Haploinsufficiency of SIN3A and KDM1A mutations lead to similar syndromes characterized by the clinical features observed with RREB1 haploinsufficiency including developmental delay and craniofacial abnormalities." (PMID 32938917, 2020). "In mice, SIN3A is required for neuronal development with mutations in SIN3A associated with Witteveen–Kolk syndrome (OMIM# 613406), a neurodevelopmental disorder characterized by developmental delay and ID." (PMID 33729157, 2021).
diabetes (4 papers, 2019 to 2023). "Of the 15 top candidate genes, ST3GAL2, AASS, ARF1 and the transcription factor SIN3A are novel candidates for predicting a refined diabetes risk and intervention response." (PMID 36790478, 2023). "Finally, six genes (Sec61a1, Insr, Sirt1, Pdpk1, Sin3a, and Sqstm1) were predicted to be associated with diabetes and obesity." (PMID 32257911, 2019). "MAP 1B, hsa-mir-4314, hsa-mir-5688, hsa-mir-583, hsa-mir-632, hsa-mir-3176, hsa-mir-4477a, hsa-mir-606, hsa-mir-1343-3p6, SIN3A, ZNF143 and SMARCE1 are the novel biomarkers for pathogenesis of obesity associated type 2 diabetes mellitus." (PMID 33902539, 2021).
lung adenocarcinoma (4 papers, 2016 to 2024). A carcinoma that arises from the lung and is characterized by the presence of malignant glandular epithelial cells. "Consistent with this, knockdown of SIN3A resulted in increased invasion in Drosophila and increased migration in A549 human lung adenocarcinoma cells." (PMID 27780928, 2016).
glioma (3 papers, 2020 to 2024). A benign or malignant brain and spinal cord tumor that arises from glial cells (astrocytes, oligodendrocytes, ependymal cells). "Another study revealed that SIN3A, a transcriptional repressor, is downregulated in glioma, and its expression is negatively correlated with miR-210." (PMID 32906592, 2020). "MiR-210/SIN3A axis was also validated to facilitate glioma cell apoptosis." (PMID 35101035, 2022). "By regulating SIN3A, miR-210 increased the survival and proliferation of glioma cells." (PMID 32906592, 2020). "Among these TFs, CTCF, POLR2A, SIN3A, and SPI1 concurrently regulated all five prognostic genes in glioma." (PMID 39491527, 2024).
ischemia (3 papers, 2013 to 2018). A hypoperfusion of the BLOOD through an organ or tissue caused by a PATHOLOGIC CONSTRICTION or obstruction of its BLOOD VESSELS, or an absence of BLOOD CIRCULATION. "RIP data showed that the enrichment of MRAK159688 with both Sin3A and coREST also increased after focal ischemia by ~3-fold." (PMID 24063527, 2013). "We observed that the expression and binding to Sin3A of EF094477 were induced after ischemia by 6.8- and 2.4-fold, respectively, and GFAP expression was also induced concomitantly." (PMID 24063527, 2013). "The RIP-chiP showed a significant increase in enrichment of 99 lncRNAs with Sin3A and 78 lncRNAs with coREST in the ischemia group compared with the sham group." (PMID 24063527, 2013).